TIAM1 (TIAM Rac1 associated GEF 1)
Description:
Guanyl-nucleotide exchange factor that activates RHO-like proteins and connects extracellular signals to cytoskeletal activities. Activates RAC1, CDC42, and to a lesser extent RHOA and their downstream signaling to regulate processes like cell adhesion and cell migration.
Synonyms: TIAM-1; NEDLDS
Tractability: Small molecule: a structure with a bound ligand is known. Antibody: its Gene Ontology location is reachable by antibodies, with high confidence; UniProt places it where antibodies can reach, with medium confidence. PROTAC: UniProt records ubiquitination sites on it; its protein half-life has been measured; a small molecule that binds it is known.
Gene: Protein-coding gene on chromosome 21 (31,117,985 to 31,559,977, reverse strand). Ensembl gene ENSG00000156299.
Subcellular location: Cell junction; Cell membrane
Subcellular location (Human Protein Atlas): Cell Junctions; Nucleoplasm; Cytokinetic bridge; Cytosol; Nuclear membrane
Pathways (Reactome):
Signal Transduction: Activated NTRK2 signals through CDK5; CDC42 GTPase cycle; G alpha (12/13) signalling events; NRAGE signals death through JNK; RAC1 GTPase cycle; RAC2 GTPase cycle; RAC3 GTPase cycle; RHOA GTPase cycle
Developmental Biology: EPH-ephrin mediated repulsion of cells; EPHB-mediated forward signaling
Cell-Cell communication: SRC activates STAT3 in a quantitative manner, through Cadherin-11 (CDH11), RAC1 and gp130 (IL6ST)
Gene Ontology:
Molecular function: guanyl-nucleotide exchange factor activity; kinase binding; protein binding
Biological process: cell migration; cell-matrix adhesion; non-canonical Wnt signaling pathway; positive regulation of cell migration; positive regulation of cell population proliferation; protein-containing complex assembly; Rac protein signal transduction; regulation of epithelial to mesenchymal transition; small GTPase-mediated signal transduction; ephrin receptor signaling pathway; positive regulation of axonogenesis; positive regulation of epithelial to mesenchymal transition; regulation of dopaminergic neuron differentiation; regulation of small GTPase mediated signal transduction; Wnt signaling pathway, planar cell polarity pathway; intracellular signal transduction; signal transduction
Cellular component: cell junction; cell-cell contact zone; cell-cell junction; cytosol; nucleoplasm; plasma membrane; synapse; anchoring junction
Genetic constraint (gnomAD): Loss-of-function variants: 62 observed, 163.16 expected, observed/expected ratio (o/e) 0.38, 90% interval 0.31 to 0.47. The upper end of that interval is the gene's LOEUF score, 0.47, which puts it in group 2 of 6, group 1 being the genes least tolerant of losing a copy. Missense variants: 1,763 observed, 2,097.4 expected, observed/expected ratio (o/e) 0.84, 90% interval 0.81 to 0.87. Synonymous variants: 822 observed, 834.09 expected, observed/expected ratio (o/e) 0.99, 90% interval 0.93 to 1.04.
Homologues: Orthologues: chimpanzee TIAM1 (99% identical), macaque TIAM1 (99% identical), rabbit TIAM1 (97% identical), pig TIAM1 (96% identical), guinea pig TIAM1 (96% identical), mouse Tiam1 (95% identical), rat Tiam1 (95% identical), dog TIAM1 (89% identical), tropical clawed frog tiam1 (78% identical), zebrafish tiam1a (63% identical), zebrafish tiam1b (61% identical). Paralogues in human: TIAM2 (39% identical), TRIO (15% identical), KALRN (13% identical), PLEKHG4B (13% identical), ARHGEF40 (11% identical), MCF2L (11% identical), PLEKHG4 (10% identical), MCF2 (10% identical), MCF2L2 (10% identical), PLEKHG1 (9% identical), SPATA13 (9% identical), ARHGEF7 (8% identical), and 10 more.
Diseases named in the same sentence as TIAM1 in open-access papers:
TIAM1 is named in the same sentence as 120 diseases in open-access papers, as found by Europe PMC text mining. Sharing a sentence is not in itself a finding about the gene and the disease. The quoted sentences say what the papers report.
breast cancer (37 papers, 2006 to 2025). A primary or metastatic malignant neoplasm involving the breast. "We have previously found that Tiam1 is overexpressed in ovarian cancer (OC), gastric cancer (GC), and breast cancer (BC) and is associated with poor survival outcomes." (PMID 38017477, 2023). "In breast cancer, Tiam1 has been implicated with invasion and metastasis, where Tiam1 overexpression was associated with high-grade breast cancer." (PMID 32322580, 2020). "Strikingly, breast cancer cells isolated from 3D culture with Tiam1-deficient fibroblasts exhibit persistent increases in migration, EMT, and cancer stem cell characteristics." (PMID 26821678, 2016). "Co-culture of human breast cancer cells with Tiam1-deficient fibroblasts induces increased cancer cell invasion into matrix, while co-culture with Tiam1-overexpressing fibroblasts induces decreased invasion." (PMID 26821678, 2016). "Tiam1-deficient fibroblasts promote metastasis in a mouse xenograft co-implantation model of human breast cancer." (PMID 26821678, 2016). "In summary, our results suggest that regulated Tiam1 expression in breast cancer-associated fibroblasts modulates breast cancer invasion, EMT, cancer stem cell populations, and metastasis through regulation of fibroblast OPN secretion." (PMID 26821678, 2016). "We therefore tested the ability of synthesized AgelA to block the effects of Tiam1-deficient fibroblasts on SUM1315 breast cancer cells in our systems." (PMID 26821678, 2016). "This suggests that increased Tiam1 expression in mammary fibroblasts decreases invasiveness, and decreased Tiam1 expression increases invasiveness, in associated human breast cancer lines in a 3D environment." (PMID 26821678, 2016). "Taken together, these findings suggest that the effects of fibroblast Tiam1 deficiency on SUM1315 breast cancer cell behavior are dependent on fibroblast OPN." (PMID 26821678, 2016). "Given the results above of OPN inhibition by gene silencing or antibody in vitro, we tested the effects of a chemical inhibitor of OPN in blocking the effects of Tiam1-deficient RMF in an accelerated in vivo model of breast cancer metastasis." (PMID 26821678, 2016). "In regards to survival, we found that high expression of Tiam1 protein was strongly associated with molecular subtype and tumor stage, which were important features associated with poor prognosis in breast cancer." (PMID 27562113, 2016). "Altering fibroblast Tiam1 expression induces changes in invasion, migration, epithelial-mesenchymal transition, and cancer stem cell characteristics in associated breast cancer cells." (PMID 26821678, 2016). "Tiam1 expression was suggested to be closely associated with motility in human breast cancer cell lines and was necessary to maintain the motile phenotype." (PMID 24661909, 2014). "The expression of TIAM1 has been shown to be associated with increased invasiveness and progression of breast carcinomas." (PMID 23704896, 2013). "Min/+ mice in a Tiam1 -/- background had a significantly reduced susceptibility to develop Wnt-induced intestinal and mammary tumours in comparison to Tiam1 +/+/Min/+ mice, and the growth of tumours that did develop was significantly impaired." (PMID 18826597, 2008). "Thus varying Tiam1 expression in mammary fibroblasts modulated cancer stem cell properties in associated breast cancer cells." (PMID 26821678, 2016). "We therefore asked whether the effects of Tiam1-deficient fibroblasts on breast cancer cell behavior were dependent on fibroblast OPN." (PMID 26821678, 2016). "Since exposure to Tiam1-manipulated fibroblasts induced changes in invasion and migration in associated breast cancer cells, we then tested whether markers of epithelial-mesenchymal transition (EMT) in PCC-SUM1315 cells were also affected." (PMID 26821678, 2016). "We therefore investigated whether Tiam1 expression in mammary fibroblasts would affect cancer stem cell populations in associated breast cancer cells." (PMID 26821678, 2016).
breast cancer (continued). "Multiple recent studies have indicated a positive correlation between boosted TIAM1 expression level and higher grade of human breast cancer." (PMID 41149035, 2025). "YAP1–TEAD4 has been implicated in TIAM1-mediated activation of Rho-family GTPase RAC1, and thus, promotes tumour metastasis in breast cancer cells." (PMID 37370765, 2023). "Evidence has confirmed that the TIAM1 gene plays an important role in a variety of tumor activities, such as colorectal cancer and breast cancer metastasis." (PMID 35022405, 2022). "Tiam1 expression is upregulated in several cancers, including breast cancer and esophageal squamous cell carcinoma, and is correlated with poor prognosis and metastasis." (PMID 32392742, 2020). "For example, a study has shown that Tiam1 expression correlated with cell motility in human breast cancer cells and is required to support the motile phenotype." (PMID 32012800, 2020). "Previous studies showed that the expression of Tiam1 gene is up-regulated in following types of carcinomas: T lymphoma, B lymphoma, pancreatic carcinoma, gastric cancer, breast cancer, and lung cancer." (PMID 29739365, 2018). "Previous expression profiling studies revealed that Tiam1 was among the most highly expressed Rac-GEFs in HER2-induced mouse mammary tumors." (PMID 28666462, 2017). "In our study, the expression of Tiam1 protein was significantly higher in breast cancers with low HER2 expression, Tiam1 expression was inverselyrelated to the HER2 expression." (PMID 27562113, 2016). "In an expanded study, 36 independent surgical specimens from 26 individual cases of breast cancer (invasive and/or in situ ductal carcinomas) had tissue available for IHC for Tiam1 and/or OPN expression." (PMID 26821678, 2016). "Univariate analysis suggested that molecular types, clinical stage, Her2 expression levels and Tiam1 expression levels were also significantly associated with DFS and 10-year OS rates of breast cancer patients." (PMID 27562113, 2016). "Consistently, our study showed that up-regulation of Tiam1 was correlated with tumor stage in breast cancer." (PMID 27562113, 2016). "At least some human breast cancers demonstrate commensurate changes in fibroblast Tiam1 and OPN expression correlating with invasiveness." (PMID 26821678, 2016). "We first tested the effect of exposure to Tiam1-modulated fibroblasts on migration of PCC breast cancer cells." (PMID 26821678, 2016). "In conclusion, Tiam1 expression is frequently up-regulated in breast cancer, and Tiam1 overexpression correlated with clinicopathological parameters." (PMID 27562113, 2016). "The localization of the Tiam1 protein was determined in the MDA-MB-231 breast cancer cell line using immunofluorescence (IF) staining." (PMID 27562113, 2016). "The proportion of samples with high Tiam1 expression was 76.5 % (117/153) in breast cancer; it was significantly higher than in DCIS (51.1 %, 35/67) or adjacent non-tumor tissues (28.6 %, 18/63)." (PMID 27562113, 2016). "The subcellular localization of Tiam1 protein was further explored by performing IF staining for Tiam1 protein in MDA-MB-231 breast cancer cells." (PMID 27562113, 2016). "Tiam1 protein expression was significantly higher in breast cancers (42.5 %, 65/153) and DCIS (40.3 %, 27/67) than in adjacent non-tumor tissues (12.7 %, 8/63)." (PMID 27562113, 2016). "In this study we tested the effect of manipulating fibroblast Tiam1 expression on the invasiveness of two aggressive breast cancer cell lines, SUM1315 and SUM159." (PMID 26821678, 2016). "In contrast, breast cancer cells exposed to Tiam1-overexpressing fibroblasts and then isolated from 3D co-cultures persistently display the opposite phenotypes." (PMID 26821678, 2016). "This study attempted to explore the role of Tiam1 protein in tumor progression and the prognostic evaluation of breast cancer." (PMID 27562113, 2016).
breast cancer (continued). "This strongly suggests a role for fibroblast Tiam1-OPN pathway in regulating breast cancer metastasis specifically." (PMID 26821678, 2016). "The staining pattern of Tiam1 protein was primarily cytoplasmicin breast cancers, but nuclear staining was also observed." (PMID 27562113, 2016). "In early-stage breast cancers, patients with low-level Tiam1 expression had higher DFS and OS rates compared with those with high-level Tiam1 expression (P = 0.021 and P = 0.043, respectively)." (PMID 27562113, 2016). "The staining results clearly showed that Tiam1 protein is mainly located in the cytoplasm of MDA-MB-231 breast cancer cells, while some nuclear staining was also observed." (PMID 27562113, 2016). "Tiam1 protein showed a mainly cytoplasmic staining pattern in breast cancer cells; however, nuclear staining was also observed." (PMID 27562113, 2016). "Tiam1 expression correlates with cell motility in human breast cancer cells and is required to support the motile phenotype." (PMID 20819206, 2010). "In summary, our studies show that Tiam1 expression correlates with motility in human breast cancer cell lines and is required to support the motile phenotype." (PMID 20819206, 2010). "Tiam1 expression and Rac activity were examined in a panel of human breast cancer cell lines that exhibit different degrees of cell motility." (PMID 20819206, 2010). "Immunofluorescence and cellular fractionations indicate that Tiam1 is found predominantly in the Golgi of breast cancer cells, and in the latter case, Tiam1 was shown to co-fractionate with a limited pool of Rac1." (PMID 20819206, 2010). "A correlation between Tiam1 expression and tumor grade has been observed in breast carcinoma, nasopharyngeal carcinoma, hepatocellular carcinoma, retinoblastoma, and prostate cancer." (PMID 20819206, 2010). "Levels of TIAM-1 were significantly higher in tumour tissue from patients who died from breast cancer compared with those who survived (p = 0.04)." (PMID 18925966, 2008). "In line with this a positive correlation has been found between Tiam1 expression levels and a high tumour grade in breast cancer." (PMID 17003780, 2006). "For example, Tiam1 interacts with protease activated receptor 1 (Par1) at the leading edge of invasive breast cancer cells, but whether this occurs in CRC is unexplored." (PMID 39493347, 2024). "TIAM1 inhibits tumorigenesis in a Ras-induced skin cancer model, and miR-31 may be a negative regulator of metastasis development in breast cancer." (PMID 37371814, 2023). "In both breast cancer and colorectal carcinoma cells, there was a positive correlation between the migration and metastatic potential of tumor cells and the expression of Tiam1." (PMID 30171257, 2019). "However, the expression of Tiam1 was correlated negatively with the invasion of renal cell carcinomas, and downregulation of Tiam1 was present during breast cancer progression." (PMID 30171257, 2019). "In addition, miRNAs regulate Tiam1-mediated migration and invasion of hepatomas, colon carcinomas, nasopharyngeal carcinomas, breast cancer, and osteosarcomas." (PMID 30171257, 2019). "In addition, the binding of the GEF T-cell lymphoma invasion and metastasis 1 (Tiam 1) to the intracellular domain of CD44v3 promotes breast cancer cellular invasion and migration." (PMID 31832018, 2019). "Also, there has been a correlation reported between TIAM1 expression and high tumor grade in human breast carcinomas." (PMID 27902969, 2017). "To determine the expression levels of Tiam1 in breast cancer patients, we performed IHC." (PMID 27562113, 2016). "To assess whether Tiam1 expression in mammary fibroblasts affects invasiveness of breast cancer cells in vitro, we adapted a 3D co-culture model of fibroblast and epithelial cell lines in extracellular matrix." (PMID 26821678, 2016).
breast cancer (continued). "Similarly, the proportion of samples with strongly positive Tiam1 expression was 42.5 % (65/153) in breast cancer and40.3 % (27/67) in DCIS, which were significantly higher than that of adjacent non-tumor tissues (12.7 %, 8/63) (P < 0.01, respectively)." (PMID 27562113, 2016). "Tiam1 may serve as a useful prognostic biomarker and a potential therapeutic target for patients with breast cancer." (PMID 27562113, 2016). "Thus the results of both tumorsphere assay and flow cytometry of cell surface markers suggested that Tiam1 expression in mammary fibroblasts modulates cancer stem cell-like populations in these breast cancer cell lines." (PMID 26821678, 2016). "Tiam1 expression is frequently up-regulated in breast cancer." (PMID 27562113, 2016). "Finally, to evaluate the possible role of the fibroblast Tiam1-OPN pathway in human cancer, we investigated the expression of Tiam1 and OPN in fibroblasts associated with human breast cancers using IHC." (PMID 26821678, 2016). "We have investigated whether the Rac exchange factor Tiam1 in the human breast cancer microenvironment has a role in regulating tumor invasion and metastasis." (PMID 26821678, 2016). "However, there are relatively few published reports evaluating the role of Tiam1 protein expression in breast cancer." (PMID 27562113, 2016). "Consistent with many other reports, Tiam1 may play an important role in tumorigenesis and malignant progression of breast cancer." (PMID 27562113, 2016). "Herein, we report that the expression of Tiam1 is important in the tumorigenesis of breast cancer and could serve as a prognostic marker." (PMID 27562113, 2016). "Moreover, survival analyses showed that DFS and 10-year OS rates were significantly lower in breast cancer patients with high Tiam1 expression than those with low Tiam1 expression." (PMID 27562113, 2016). "Finally, in human breast cancer samples Tiam1 expression is significantly decreased in fibroblasts associated with invasive human breast cancers compared to fibroblasts associated with ductal carcinoma in situ (DCIS)." (PMID 26821678, 2016). "Similarly, for patients with late-stage breast cancer, the expression status of Tiam1 protein was also correlated with DFS and 10-year OS rates (P = 0.003 and P = 0.007, respectively)." (PMID 27562113, 2016). "Furthermore, multivariate analysis suggested that Tiam1 expression is a significant independent prognostic factor along with tumor stage in patients with breast cancer." (PMID 27562113, 2016). "In addition, Tiam1 was significantly higher in breast cancers with high Ki-67 expression (50.0 %, 51/102) than in cases with low Ki-67 expression (27.5 %, 14/51) (P = 0.008)." (PMID 27562113, 2016). "Consequently, the molecular mechanism of Tiam1-regulation in breast cancer needs the further study to clarify." (PMID 27562113, 2016). "Further investigation is required to determine the role of Tiam1 in breast cancer progression." (PMID 27562113, 2016). "Additionally, Tiam1 increases invasion and metastasis in several human cancer cell lines including melanoma and breast cancer." (PMID 24069171, 2013). "Although our results clearly indicate that Tiam1 is required for breast cancer cell motility, we also wished to determine whether it was sufficient to induce a motile phenotype." (PMID 20819206, 2010). "Although it was previously reported that Tiam1 expression is elevated in human breast cancer cell lines, the activity of Tiam1 in these cells is unknown." (PMID 20819206, 2010). "Consistent with this oncogenic activity, an examination of 40 human tumor cell lines including neuroblastomas, melanomas, hematopoietic tumors, lung carcinomas, colon carcinomas, and breast carcinomas revealed that Tiam1 was expressed in virtually all the cell lines." (PMID 20819206, 2010).